RNU5B-3P (RNA, U5B small nuclear 3, pseudogene)
Gene: Small nuclear RNA gene on chromosome 3 (45,034,474 to 45,034,588, reverse strand). Ensembl gene ENSG00000252410.
Homologues: Orthologues: chimpanzee U5 (97% identical), pig U5 (56% identical), rabbit U5 (51% identical), guinea pig U5 (33% identical). Paralogues in human: RNU5E-4P (64% identical), RNU5B-4P (62% identical), RNU5E-7P (62% identical), RNU5A-7P (61% identical), RNU5E-10P (61% identical), RNU5E-6P (61% identical), RNU5F-4P (61% identical), RNU5A-3P (60% identical), RNU5B-2P (60% identical), RNU5A-4P (59% identical), RNU5A-8P (59% identical), RNU5A-5P (58% identical), and 13 more.